NEUROD2 (neuronal differentiation 2)
Description:
Transcriptional regulator implicated in neuronal determination. Mediates calcium-dependent transcription activation by binding to E box-containing promoter. Critical factor essential for the repression of the genetic program for neuronal differentiation; prevents the formation of synaptic vesicle clustering at active zone to the presynaptic membrane in postmitotic neurons. Induces transcription of ZEB1, which in turn represses neuronal differentiation by down-regulating REST expression. Plays a role in the establishment and maturation of thalamocortical connections; involved in the segregation of thalamic afferents into distinct barrel domains within layer VI of the somatosensory cortex. Involved in the development of the cerebellar and hippocampal granular neurons, neurons in the basolateral nucleus of amygdala and the hypothalamic-pituitary axis. Associates with chromatin to the DPYSL3 E box-containing promoter (By similarity).
Synonyms: bHLHa1; NDRF; DEE72; EIEE72
Tractability: PROTAC: ubiquitination databases record sites on it; its protein half-life has been measured.
Gene: Protein-coding gene on chromosome 17 (39,603,536 to 39,609,777, reverse strand). Ensembl gene ENSG00000171532.
Subcellular location: Nucleus
Gene Ontology:
Molecular function: sequence-specific double-stranded DNA binding; DNA-binding transcription factor activity; DNA-binding transcription factor activity, RNA polymerase II-specific; E-box binding; protein heterodimerization activity; DNA binding; DNA-binding transcription activator activity, RNA polymerase II-specific; protein dimerization activity; RNA polymerase II transcription regulatory region sequence-specific DNA binding
Biological process: axon development; cellular response to calcium ion; cellular response to electrical stimulus; cerebellar cortex development; negative regulation of synapse maturation; nervous system development; positive regulation of calcium-mediated signaling; positive regulation of neuron differentiation; positive regulation of synapse maturation; positive regulation of synaptic plasticity; positive regulation of transcription by RNA polymerase II; protein ubiquitination; regulation of transcription by RNA polymerase II; sensory organ development; regulation of DNA-templated transcription
Cellular component: chromatin; nucleus
Genetic constraint (gnomAD): Loss-of-function variants: 5 observed, 11.73 expected, observed/expected ratio (o/e) 0.43, 90% interval 0.22 to 0.9. The upper end of that interval is the gene's LOEUF score, 0.9, which puts it in group 3 of 6, group 1 being the genes least tolerant of losing a copy. Missense variants: 376 observed, 490.5 expected, observed/expected ratio (o/e) 0.77, 90% interval 0.7 to 0.83. Synonymous variants: 277 observed, 237.1 expected, observed/expected ratio (o/e) 1.17, 90% interval 1.06 to 1.29.
Homologues: Orthologues: chimpanzee NEUROD2 (100% identical), macaque NEUROD2 (99% identical), mouse Neurod2 (98% identical), dog NEUROD2 (98% identical), pig NEUROD2 (98% identical), rat Neurod2 (98% identical), guinea pig NEUROD2 (96% identical), tropical clawed frog neurod2 (70% identical), zebrafish neurod2 (58% identical), Caenorhabditis elegans ngn-1 (16% identical), Drosophila melanogaster tap (15% identical), Caenorhabditis elegans lin-32 (10% identical), and 2 more. Paralogues in human: NEUROD1 (47% identical), NEUROD6 (43% identical), NEUROD4 (37% identical), ATOH1 (18% identical), NEUROG2 (18% identical), NEUROG1 (17% identical), BHLHE22 (16% identical), NEUROG3 (16% identical), OLIG2 (15% identical), BHLHA15 (15% identical), ATOH8 (14% identical), OLIG3 (14% identical), and 3 more.